HGF (hepatocyte growth factor)
Diseases named in the same sentence as HGF in open-access papers (continued):
Sharing a sentence is not in itself a finding about the gene and the disease.
lung carcinoma (continued). "The purpose of this study was to determine whether bufalin, a major bioactive component of Venenum Bufonis, could reverse HGF-induced resistance to reversible and irreversible EGFR-TKIs in mutant lung cancer cells PC-9, HCC827, and H1975." (PMID 23533466, 2013). "In conclusion, we showed here that bufalin could reverse HGF-induced resistance to EGFR-TKIs by inhibiting Met/PI3K/Akt pathway and activating death signaling in EGFR mutant lung cancer cells." (PMID 23533466, 2013). "HGF increases COX-2 protein expression by 3-fold over basal levels via both the extracellular signal-regulated kinase 1/2 (ERK) and the p38 pathway that induced prostaglandin E2 (PGE2); these seem to enhance lung cancer invasion." (PMID 23878598, 2013). "The new generation EGFR-TKI inhibited the growth of lung cancer cells containing the gatekeeper EGFR-T790M mutation, but did not inhibit the growth of cells with Met amplification or HGF overexpression." (PMID 24386407, 2013). "Transcriptomic data from METex14Del-expressing cells, stimulated or not by HGF, were mapped onto this lung cancer reference network and revealed activation of a major regulatory node composed mainly by the highly influential transcription factors ETS1, FOSL1 and SMAD3." (PMID 41184222, 2025). "Our reverse engineering approach to infer the first lung cancer-specific gene regulatory network from the lung cancer cell dataset without any a priori knowledge allowed us to distinguish two different states of cell activation: HGF-stimulated or not." (PMID 41184222, 2025). "In addition, hepatocyte growth factor (HGF), an inducer of HIF-1α, suppresses miR-519c maturation through an Akt-dependent pathway, indicating the important role of the HGF/miR-519c/HIF-1α axis in modulating angiogenesis in lung cancer." (PMID 35918758, 2022). "Another multispecific DARPin targeting VEGF and hepatocyte growth factor (HGF), while also binding to human serum albumin (HSA) for increased half‐life, is currently tested in combination with a tyrosine kinase inhibitor in a clinical trial for patients with non‐small cell lung cancer (NCT03418532)." (PMID 32794303, 2021). "Importantly, anti-HGF neutralizing antibody and the natural HGF inhibitor NK4 significantly overcome the gefitinib resistance in culture and in tumor xenografts raised by lung cancer cells admixed with HGF-producing human fibroblasts in mice treated with gefitinib." (PMID 31067787, 2019). "Potentiation of EGFR action by MET in lung cancer has been found to be independent of HGF leading to speculation in favor of an intracellular lateral signaling cascade." (PMID 29348142, 2018). "However, neither PDBu nor HGF upregulated N-WASP expression in CTTN-knockdown or miR-182 overexpressed lung cancer cells." (PMID 29986736, 2018). "Interestingly, analysis of plasma samples from healthy heavy smokers enrolled in a CT-screening program for early lung cancer detection revealed a strong correlation between smoke exposure or COPD and circulating levels of HGF (p = 0.001 and p = 0.041 respectively)." (PMID 29558956, 2018). "Activation of the HGF/c-MET signaling pathway contributes to the promotion of tumor cell motility, scattering, invasion, and metastasis, suggesting it to be a negative prognostic indicator for cell survival and recurrence in some solid tumors including lung cancer." (PMID 29069748, 2017). "Similarly, HGF treatment of lung cancer derived A549-shScr cells, but not A549-shRan cells, resulted in a significant increase in cell adhesion (p < 0.05), migration (p < 0.05), and invasion (p < 0.05)." (PMID 27716616, 2016). "Here, we show that in response to HGF, HUWE1 ubiquitylates TIAM1 on lysine 595, triggering its proteasomal degradation predominantly at cell-cell adhesions, thereby enabling disassembly of cell junctions and induction of cell migration and invasion, including in lung carcinoma cells." (PMID 25543140, 2015).
lung carcinoma (continued). "Accumulating evidence has suggested that inhibition of HGF/c-Met signaling could serve as a useful therapeutic strategy for attenuating the growth and metastasis of various human cancers, including HCC, colorectal cancer, lung cancer, head and neck cancer, cervical cancer, etc.." (PMID 37835375, 2023). "Notably, FGF family members and HGF were identified as the most abundant factors in CAF supernatants, and were able to confer resistance to lapatinib treatment to advanced esophageal squamous cell carcinoma (ESCC) cells, extending their role beyond lung cancer." (PMID 36324182, 2022). "Therefore, we can conclude that in lung cancer cells, Grb2, SCOS and PKCμ are the potential target molecules for SIPA1, thus promoting the recycling of MET, in order to maintain the MET receptor at a high level, thereby enabling the transmission of the HGF signal within the cells." (PMID 33917539, 2021). "However, whether miR‐1‐3p and miR‐206 can overcome HGF‐induced gefitinib resistance in EGFR mutant lung cancer is not clear." (PMID 29664235, 2018). "However, there is no report showing that bufalin could overcome HGF-induced EGFR-TKIs resistance in EGFR mutant lung cancer cells when combined with gefitinib or afatinib." (PMID 23533466, 2013). "However, there are limited studies investigating the function of SIPA1 in lung cancer and the mechanism of SIPA1 in cancer development and metastasis remains largely unknown, particularly the role of SIPA1 in regulating the TJs and reacting to HGF signaling in lung cancer cells." (PMID 33917539, 2021). "Mutations in c-Met that confer its constitutive activation independent of its ligand (hepatocyte growth factor, HGF) has been observed and autocrine up-regulation of HGF has been reported in lung cancer." (PMID 29296173, 2017). "Furthermore, HGF-treated A549 and 95D cells have undergone EMT and exhibited enhanced invasiveness and motility, and c-Met inhibitors, SU11274 can suppress the effects of HGF, suggesting HGF/c-Met signaling pathway could be a therapeutic target of lung cancers." (PMID 26919096, 2016). "For example, lung cancer cell characteristics are independent of their MSC counterparts while GC cell proliferation, migration and invasion are dependent on the activation of hepatocyte growth factor (HGF)/c-MET signalling pathway specifically induced by HGF from GC-MSCs." (PMID 29795331, 2018).
hepatocellular carcinoma (174 papers, 2007 to 2025). A malignant tumor that arises from hepatocytes. "In hepatocellular carcinoma, aberrant activation of the HGF/MET axis promotes angiogenesis and is closely associated with metastasis and drug resistance." (PMID 40860829, 2025). "MET codes for a receptor which is a transmembrane protein; its ligand is hepatocyte growth factor and mutations in the gene have been linked with development of hepatocellular carcinoma." (PMID 40489530, 2025). "Sustained activation of hepatocyte growth factor (HGF)/c-MET signaling is a major driver of hepatocellular carcinoma (HCC) progression, but underlying mechanism is unclear." (PMID 37061723, 2023). "In hepatocellular carcinoma cells, HGF-induced EMT was associated with decreased expression of MGAT3 and increased MGAT5 expression." (PMID 34356834, 2021). "Hepatocyte growth factor (HGF) signaling through its receptor Met has been implicated in hepatocellular carcinoma tumorigenesis and progression." (PMID 31452933, 2019). "The studies performed in patients with chronic hepatitis C have demonstrated that higher HGF concentrations were associated with increased fibrosis and angiogenesis and have indicated a higher risk of development of hepatocellular cancer." (PMID 26448742, 2015). "CDK5 kinase regulatory subunit-associated protein 3 (CDK5RAP3) in hepatocellular cancer and hepatocyte growth factor (HGF) and follicle-stimulating hormone (FSH) in ovarian cancer activate PAK4 to promote cell migration." (PMID 25975262, 2015). "The Hepatocyte Growth Factor (HGF)/c-Met signaling pathway regulates hepatocyte proliferation, and pathway aberrations are implicated in the invasive and metastatic behaviors of hepatocellular carcinoma (HCC)." (PMID 22912725, 2012). "Apart from tumour-associated M2 macrophages, cancer-associated fibroblasts and hepatoma cells also produce a significant amount of HGF that may contribute to the acquisition of sorafenib resistance." (PMID 31130723, 2019). "The epithelial mesenchymal transition of HGF-treated Huh7 hepatocellular carcinoma cells is associated with a decreased affinity for a panel of T/Tn-specific lectins including ACL (Amaranthus caudatus), BPL (Bauhinia purpurea), jacalin, SBA (soybean) and SNA (Sambucus nigra)." (PMID 28598369, 2017). "However, upregulation of HGF and c-Met have been associated with tumor progression and metastasis in hepatocellular carcinoma (HCC)." (PMID 23723997, 2013). "For example, TAMs in hepatocellular carcinoma facilitate tumor progression by upregulating hepatocyte growth factor expression." (PMID 41474538, 2025). "On the other hand, the HGF/MET axis promotes the invasive growth of cancers; therefore, evaluation of HGF/MET targeted therapy is performed for hepatocellular carcinoma and cholangiocarcinoma (CCA)." (PMID 40076928, 2025). "A recent study based on the hepatocellular carcinoma model indicated that sorafenib increased the synthesis and secretion of hepatocyte growth factor (HGF) by TAMs." (PMID 38787372, 2024). "Overexpression of Hepatocyte growth factor (HGF) and Cellular-mesenchymal epithelial transition factor (c-Met) occurred after stimulation of hepatocellular carcinoma cells (HCC) with Tetrachloromethane and Diethylnitrosamine." (PMID 39055491, 2024). "To test this, we determined Gab1 expression following co-treatment with CCL4 and HGF using the mouse hepatoma cell line Hepa1-6 cells." (PMID 38935609, 2024). "IQGAP1 knockdown in HepG2 hepatocellular carcinoma cells significantly increases HGF-stimulated MET activation and signaling to Akt and ERK." (PMID 36766826, 2023). "HGF secreted by CAFs can regulate CSCs stemness of hepatocellular carcinoma and colorectal cancer by activating c-Met/FRA1/HEY1 signaling, Wnt/β-catenin and PI3K signaling, respectively." (PMID 36910604, 2023). "The binding of HGF to its receptor c-Met can trigger Hif1a expression in PI3K-dependent mode in HepG2 hepatoma cells." (PMID 37842051, 2023).
hepatocellular carcinoma (continued). "For instance, in hepatoma HepG2 cells, a synergistic association exists between the HGF/c-Met and TRK signaling pathways, and the simultaneous inhibition of c-Met and TRKB exhibits a synergistic inhibitory effect on hepatoma." (PMID 37945598, 2023). "α-SMA(+) CAFs can enhance hepatocellular carcinoma (HCC) resistance to chemotherapy by stimulating the HGF-MET-FRA1-HEY1 cascade reaction." (PMID 37666813, 2023). "M2, but not M1, tumor-associated macrophages not only promote proliferation, colony formation and migration of hepatoma cells but also significantly confer tumor resistance to sorafenib via sustaining tumor growth and metastasis by secreting HGF." (PMID 37842051, 2023). "Consistent with our results, IQGAP1 knockdown in Snu-449 hepatocellular carcinoma cells was recently reported to enhance HGF-stimulated MET activation and phosphorylation of Akt." (PMID 36766826, 2023). "Increased levels of HGF are found in liver diseases, such as acute hepatitis, chronic hepatitis, liver cirrhosis, hepatocellular carcinoma, and fulminant hepatic failure." (PMID 36297236, 2022). "HSP60 is involved in hepatocyte growth factor (HGF)-induced ERK activation to promote cell migration in hepatocellular carcinoma." (PMID 35864539, 2022). "As a coreceptor in Wnt and HGF signaling, glypican-3 (GPC-3) promotes the progression of tumor and is associated with a poor prognosis in hepatocellular carcinoma (HCC)." (PMID 36091074, 2022). "The secreted hepatocyte growth factor (HGF) regulates the c-Met/FRA1/HEY1 axis in hepatocellular carcinoma." (PMID 36550571, 2022). "CAFs critically involved in hepatocellular carcinoma chemoresistance by enhancing the CD73 + positive hepatocellular carcinoma cancer cells through the HGF-Met-ERK1/2 pathway." (PMID 36550571, 2022). "In hepatocellular carcinoma, hepatocyte growth factor activates the c-MET and MEK-ERK1/2 pathways, and upregulates the expression of KRT19." (PMID 34659572, 2021). "FUT8 was increased in EMT-induced by HGF in hepatocellular carcinoma cells and in non-small cell lung cancer (NSCLC)." (PMID 34356834, 2021). "Treatment of hepatocellular carcinoma cells with HS20 was revealed to block the activation of the HGF/Met pathway, and consequently to inhibit HGF-induced cell migration, motility, and 3D-spheroid formation, as well as in vivo liver tumour growth." (PMID 34858858, 2021). "For instance, hepatocyte growth factor (HGF) production by TAMs accelerates hepatocellular carcinoma development." (PMID 34281293, 2021). "Activation of this axis and consequent development of in vitro and in vivo tolerance to sorafenib has been found in hepatocellular carcinoma cells following EV-regulated delivery of hepatocyte growth factor (HGF)." (PMID 33670185, 2021). "According to recent studies, it has been reported that HGF promoted growth of hepatocellular carcinoma (HCC) cells." (PMID 34683124, 2021). "In human hepatoma HepG2 cells, HGF-induced phosphorylation of c-Met was suppressed after treatment with GD1a." (PMID 34064863, 2021). "Hepatocellular carcinoma-derived EVs have been shown to activate the HGF/MET/AKT pathway in sensitive hepatocellular carcinoma cells, thereby inducing sorafenib resistance." (PMID 33080788, 2020). "It has been published that exposure of hepatoma cell lines to HGF induced transcription of ETS1 and, subsequently, MMPs, whereas silencing of ETS1 downregulated production of MMPs." (PMID 32977498, 2020). "Inhibition of HGF in vitro decreases proliferation and invasive potential of several hepatoma cell lines." (PMID 32899119, 2020). "Conditioned media from HGF producing TANs promoted hepatoma cell migration, whereas the media from blood derived neutrophils, which produce less HGF did not." (PMID 32117721, 2020). "In conclusion, we demonstrated that tumour-associated M2 macrophages but not M1 macrophages increase the growth and migration of hepatoma cells, confer hepatoma resistance to sorafenib treatment by secreting HGF." (PMID 31130723, 2019).
hepatocellular carcinoma (continued). "The HGF/Met axis pathway represents an attractive therapeutic target for many cancers including hepatocellular carcinoma (HCC) because of its putative role in tumorigenesis and invasion." (PMID 31452933, 2019). "HGF chemoattracts more macrophages migrated from surrounding area, regulates the distribution of M2 macrophages and increases hepatoma resistance to sorafenib in a feed-forward manner." (PMID 31130723, 2019). "Substitute of M2-CM with recombinant human HGF mitigated the capabilities of sorafenib to inhibit the growth, colony formation and migration of hepatoma cells." (PMID 31130723, 2019). "For example, TAMs in hepatocellular carcinoma contribute to tumor development by inducing hepatocyte growth factor (HGF) expression." (PMID 31629410, 2019). "Addition of anti-HGF to M2-CM abolished the activities of M2-CM on sorafenib, suggesting that HGF in M2-CM play the predominant role in hepatoma resistance to sorafenib conferred by M2 macrophages via sustaining tumour growth and metastasis." (PMID 31130723, 2019). "More importantly, the HGF/c-Met signaling is one of the most frequently dysregulated pathways in hepatocellular carcinoma, targeting of this pathway directly suppressed tumor growth and metastasis by a dual blockade of VEGFR2 and c-Met activation." (PMID 29416603, 2018). "HGF/c-Met is activated in approximately 50% of hepatocellular carcinomas (HCC), and expression levels of these proteins are associated with poor clinical prognosis for this disease." (PMID 29455668, 2018). "Sorafenib inhibits EMT in hepatocellular carcinoma, attenuates HGF secretion in polarized macrophages, decreases plasma HGF levels, and abolishes polarized macrophage-induced activation of the HGF receptor Met." (PMID 30286728, 2018). "Second, deguelin down-regulated the proangiogenic characteristics in hepatocellular carcinoma cells by inhibiting the secretion of VEGF through the inhibition of HGF-c-Met signaling pathway." (PMID 29416603, 2018). "MACC1 inhibits the cell apoptosis by targeting the HGF/c-MET/PI3K/AKT signaling pathway in hepatocellular carcinoma." (PMID 28348518, 2017). "Hepatocyte growth factor (HGF) signaling has been shown to facilitate Plasmodium berghei sporozoite infection in hepatoma cells, possibly by conferring resistance to induced cell death." (PMID 28220125, 2017). "Altered glycan profiles were detected in hepatocellular carcinoma HUH7 cells during hepatocyte growth factor (HGF)-induced EMT by a lectin microarray." (PMID 28763000, 2017). "In fact, it was reported that HGF signaling in hepatoma cell lines favors sporozoite transition to the invasive mode and cell survival upon Plasmodium sporozoite infection, in a species-specific fashion." (PMID 28220125, 2017). "Hepatocyte growth factor (HGF)-induced c-Met signaling plays critical roles in the progression of hepatocellular carcinoma (HCC)." (PMID 28214467, 2017). "To investigate the role of Arf6 in HGF-dependent cell functions of hepatocytes, we employed the human hepatocellular carcinoma cell line HepG2 cells as a model system." (PMID 28842595, 2017). "HGF‐induced intrahepatic metastasis in mice, injected with the human hepatoma cell line HepG2, were prevented by Dynasore, the inhibitor of dynamin and endocytosis, suggesting novel therapeutic endosomal targets for the treatment of HGF‐induced HCC." (PMID 26506511, 2016). "Our findings suggest that sorafenib inhibits polarized macrophage-induced EMT in hepatocellular carcinoma cells via the HGF-Met signaling pathway." (PMID 27203677, 2016). "The mRNA levels of HGF and Met in hepatocellular carcinoma are markedly increased compared with those in common liver cells." (PMID 27203677, 2016). "Taken together, these results indicate that sorafenib blocks only polarized macrophage-activated HGF-Met signaling in hepatocellular carcinoma cells." (PMID 27203677, 2016).